STAT3 (signal transducer and activator of transcription 3)
Diseases named in the same sentence as STAT3 in open-access papers (continued):
Sharing a sentence is not in itself a finding about the gene and the disease.
tumor (continued). "Using SP in animal experiments effectively suppressed tumor growth in tumor tissues by regulating STAT3 and p38." (PMID 39247603, 2024). "Activating the ERBB family leads to the stimulation of key pathways such as the MAPK pathway, STAT3 signalling, and the PI3K–Akt pathway, which are primarily associated with cell proliferation and tumour cell survival." (PMID 39063109, 2024). "In GBM, STAT3 is reported to directly promote cell survival by enhancing expression of Bcl-2-like protein 1, driving the inhibition of cell death and promoting tumour cell proliferation." (PMID 38615034, 2024). "Based on tumor-targeting ability and the inhibition of the STAT3 and NF-κB signaling pathways, we then investigated the anti-tumor effect and the immune environment remodeling in the BCa model." (PMID 39085255, 2024). "A large body of evidence suggests that signal transducer and activator of transcription 3 (STAT3) has tumor-promoting properties that it exerts in a context-dependent fashion." (PMID 38573819, 2024). "Presented results provide new insights into the biology of USP21, suggesting novel mechanisms for controlling STAT3 activity and mitochondrial function in tumor cells." (PMID 39305962, 2024). "The IL-6/STAT3/xCT axis functioned as a novel mechanism that promoted tumor development, and thus, IL-6 can be used as a target for tumor treatment and prevention." (PMID 39099925, 2024). "There is considerable evidence demonstrating the importance of STAT3 in cellular transformation and tumor initiation of PDAC." (PMID 38464736, 2024). "STAT3 promotes the proliferation and growth of lung cancer cells and inhibits their apoptosis following tumor formation." (PMID 39068486, 2024). "Reduction of PDLIM2 in these cases results in the constitutive activation of transcription factors, including NF-κB and STAT3, leading to increased tumor inflammation and supporting tumor growth." (PMID 38880883, 2024). "In the PPI results, we observed that molecules such as MAPK14, ATP6V1, Itgbs, MB2, STAT3, PKM, ACSS3, and MYL9, which are associated with signal transduction, inflammation, and tumor invasion, exhibited more active interactions with other molecules." (PMID 38203782, 2024). "Butyrate administration significantly decreased the tumor size and levels of the immunosuppressive markers (PD-L1 and IL-10), their regulators (NF-KB and STAT3), and cancer growth factor (VEGF and GDF-15) in cancer tissues." (PMID 38197259, 2024). "As such, determination of the oncogenic or tumor suppressive function of STAT3 should inform the decision to employ STAT3 inhibition as a therapeutic strategy." (PMID 38339245, 2024). "STAT3/miRNA/IL-6 feedback loops promote tumor cell proliferation and epithelial–mesenchymal transition (EMT), and accelerate the development of various diseases, such as cervical squamous cell carcinoma (CSCC)." (PMID 38172648, 2024). "Accumulating evidence has shown that STAT3 signaling is crucial for tumor microenvironment and cancer development, including cell survival and proliferation." (PMID 38720012, 2024). "STAT3 is a signal transducer and transcription activator that dimerized and translocated to the nucleus upon phosphorylation, regulates tumor-related genes (such as Bcl-2 and Snail) involved in cell growth, apoptosis, and migration." (PMID 38182570, 2024). "Aberrant activation of the JAK2/STAT3 signaling pathway deteriorates cancer progression and induces an immunosuppressive tumor microenvironment." (PMID 38686052, 2024). "High expression of STAT3 is shown to inhibit DC maturation, which in turn leads to immature DC accumulation and subsequent immunosuppression, leading to tumor cell escape." (PMID 38571491, 2024).
tumor (continued). "For example, the release of the proinflammatory cytokines TNF-ɑ, NFkB and IL-6 by TAMs induces PD-L1 expression in tumor cells via the NF-kB and STAT3 signaling pathways." (PMID 39516356, 2024). "The JAK/STAT3 signaling mediates the impact of IL-6 on tumor cell proliferation, survival, invasion, and metastasis as well as the suppression of anti-tumor immunity." (PMID 39247610, 2024). "STAT3 also plays an important role in immune response by regulating immune checkpoint proteins and tumor environmental cytokines." (PMID 39085755, 2024). "PDLIM2 repression in tumor cells thus results in the persistent activation of STAT3 and RelA, leading to MHC-I downregulation and high expression of tumor growth-related genes." (PMID 39718207, 2024). "In our previous study, we demonstrated that the TAMs preferentially secrete TGFBI, which promotes GSC-driven tumor growth through integrin αvβ5-Src-Stat3 signaling." (PMID 39346536, 2024). "In the tumor microenvironment, STAT3, which is predominantly activated by IL-10 and IL-21, but not by IL-6, enhances the effector function and survival of Texterm cells, thereby improving tumor regulation." (PMID 38582965, 2024). "Tumor-derived IL-6 stimulates the STAT3 pathway in CAFs, sustaining the CSC-like characteristics of tumor cells by prompting CAFs to release MMPs." (PMID 39092186, 2024). "It has been well established that IL-6 and STAT3 are required for survival and proliferation of tumor-initiating intestinal epithelial cells." (PMID 38520006, 2024). "In GBM, RORα reduced tumour-promoting inflammation by downregulation of the JAK2 (Janus Kinase 2)/STAT3 (Signal Transducer And Activator Of Transcription 3) /IL-6 (Interleukin 6) and the TNF-α/NF-κB pathway." (PMID 38378853, 2024). "In the present study, we report a GSCs-mediated angiogenesis manner, in which IFITM3 expressed in GSCs regulates JAK/STAT3 signaling pathway that preferentially stimulates bFGF production, leading to tumor angiogenesis." (PMID 38218875, 2024). "On the other hand, STAT3 plays an important role in tumor development and aberrant phosphorylation of STAT3 accumulates in nearly 70% of cancers and is associated with disease progression and poor prognosis." (PMID 38990440, 2024). "Under the condition of co-culture of tumor-associated macrophages and SW480 cells, PDIA3 can promote the expression of PD-1 by enhancing the phosphorylation of STAT3, and PD-1 is then secreted extracellularly." (PMID 38761176, 2024). "Metformin increases STAT3 in advanced PCa cases, leading to significant tumor growth attenuation, underscored by reduced mTORC1/CREB and AR levels in a PCa murine model." (PMID 38811984, 2024). "In human glioblastoma, C/EBPβ and Stat3 have been reported as master transcriptional regulators of mesenchymal transformation, a characteristic of tumor aggressiveness, and prognostic factors for poor clinical outcome." (PMID 39858431, 2024). "The potential of the STAT3 signaling pathway to act in both a tumor suppressive and oncogenic manner led us to investigate specific downstream targets – namely Vegf A, Mdr1, cMet - which were found to be upregulated under oncogenic levels of NRN1." (PMID 38705997, 2024). "In melanoma tumor-bearing mice, LbL-AuNP showed a significant (p < 0.05) reduction in tumor volume, tumor weight, and STAT3 protein expression compared with control treatments." (PMID 38831883, 2024). "By upregulating the expression of immunosuppressive molecules such as PD-L1, TGF-β1, VEGF, IL-6 and IL-10, STAT3 promotes tumor growth and immune evasion." (PMID 38683372, 2024). "This chronic inflammatory state can enhance tumor growth, angiogenesis, and metastasis by interacting with other inflammatory pathways like NF-κB and STAT3." (PMID 39201599, 2024). "Extrinsic mechanisms encompass the activation of the STAT3 pathway with ionizing radiation or with cytokines produced by inflammatory cells within the tumor microenvironment, thereby facilitating tumor development." (PMID 38920657, 2024).
tumor (continued). "To clarify the mechanism of ‘the impact of IL-6 on TAMs, we performed GSVA analysis on single-cell data and found that the downstream JAK/STAT3 pathway of IL-6 was significantly activated and further increased with tumor progression." (PMID 38424624, 2024). "(A) Subcutaneous tumor formation in nude mice by KP MEFs expressing vector alone, STAT3 KO, STAT3 K658Y or STAT3 Y640F (104 cells per injection site, n=4 for each cell type)." (PMID 38573819, 2024). "For instance, curcumin, by upregulating PIAS3 in ovarian and endometrial cancer cells, inhibits STAT3 activation and restrains tumor cell growth." (PMID 38920657, 2024). "Melatonin prevents migration and invasion in this tumor cell line by blocking the EMT activation mediated by the IL-6/STAT3, AKT/GSK-3β and β-catenin pathways." (PMID 38473317, 2024). "p-STAT3 promotes tumour growth mainly by promoting the transcription of cell proliferation and survival genes, such as c-Myc, cyclin D1 and Bcl-xL." (PMID 38504172, 2024). "Studies have shown that alantolactone inhibited the activation of STAT3 in a variety of tumor cells." (PMID 38822350, 2024). "STAT3 plays critical roles in tumor initiation, progression, and metastasis by regulating expression of downstream target genes." (PMID 38886396, 2024). "In conclusion, Y-A exerts anti-tumor effects by inducing apoptosis and inhibiting STAT3 signaling in HepG2 cells and LM-3 cells, both in vitro and in vivo." (PMID 39056720, 2024). "WMW regulated NF-kB/IL-6/STAT3 pathway to balance between tumor-promoting and tumour-suppressing bacteria, thereby attenuating CAC." (PMID 38783955, 2024). "Different small molecules have been reported to exert anti-tumor effects by inhibiting the JAK/STAT3 pathway." (PMID 38892472, 2024). "The pro-tumoral activities of IL-6 are related to its ability to directly act on tumor cells by activating STAT3, which in turn promotes their proliferation, survival, and invasive potential." (PMID 39281678, 2024). "In conclusion, we have shown that LIF promotes the establishment of an adaptative survival niche in the tumor microenvironment, through the over-phosphorylation of STAT3 leading to FGFR4 overexpression." (PMID 37945798, 2024). "Elevated levels of signal transducer and activator of transcription 3 (STAT3) play a pivotal role in persistent activation of key cancer hallmarks such as metastasis, tumor formation, drug resistance, and cancer stemness 12 and are linked to poor prognosis." (PMID 39664573, 2024). "Tumor cell-released autophagosomes (TRAPs) can convert macrophages into an M2-like phenotype via the TLR4/MyD88/p38/STAT3 pathway, subsequently suppressing T cell activation." (PMID 39430253, 2024). "Copper up‐regulates the expression of PD‐L1 by stimulating the IL6/JAK/STAT3 signalling pathway, leading to the exhaustion of T cells and the inability to kill tumour cells." (PMID 38801402, 2024). "This dual regulatory action is crucial, as DARPP-32 overexpression is described in over 70% of cancers, while phosphorylated STAT-3 is integrally involved in tumor development." (PMID 39767693, 2024). "Specifically, we found that PQR309 plus gemcitabine synergistically suppressed NPC tumor activity by downregulating STAT3-mediated HSP60 expression." (PMID 38555280, 2024). "The effect on STAT3 and increased PD-L1 has been shown in several cancer types, leading to T cell suppression and tumour cell immune evasion plus further contribution to bacteria immune evasion." (PMID 38535967, 2024). "STAT3 can also inhibit the anti-tumor ability of dendritic cells by inhibiting the maturation, activation, and antigen presentation." (PMID 38495483, 2024).
tumor (continued). "Since STAT3 itself is an important driver of tumor progression in various cancers and its constant phosphorylation leads to deregulated activity, therapeutic approaches have been pursued to block STAT3 function." (PMID 39544930, 2024). "Evidence has shown that activation of STAT3 stimulated by IL-10 and TGFβ in tumor-infiltrating DCs impedes CD8+ T cell function, and contributes to accumulation and proliferation of tolerogenic Treg cells inside tumors." (PMID 38245798, 2024). "Glutamine has been shown to shift cancer cells towards utilising oxidative phosphorylation for bioenergetics and/or activate STAT3 to promote tumor progression 33-35." (PMID 39431017, 2024). "The release of proinflammatory cytokines, such as IL-1, IL-6, IL-8, and TNF-α, by immune, stromal, and tumor cells activates tumor proliferative and pro-survival signaling pathways, such as NF-κB and STAT3." (PMID 38473997, 2024). "In poorly differentiated tumor samples, the expression levels of STAT3 and STAT5b were significantly increased, with STAT3 expression being particularly associated with shorter patient survival." (PMID 39290697, 2024). "In CC cases with heterogeneous EMR1 expression, specific JAK-STAT genes (JAK2, JAK3, STAT1, STAT2, and STAT3) were upregulated in the EMR1-H/L ROI compared to those in the EMR1-N ROI within the same tumor." (PMID 38673975, 2024). "Because STAT3 is relevant in both cancer and cancer-related cells, noninvasive STAT3 imaging techniques will contribute to elucidating the spatiotemporal function of STAT3 within the tumor microenvironment and development of STAT3-based personalized medicine." (PMID 38834900, 2024). "The IL-6/JAK/STAT3 signaling pathway drives tumor cell proliferation, invasion and metastasis and suppresses anti-tumor immune responses by reducing tumor antigen expression and decreasing responses to genotoxicity." (PMID 39007138, 2024). "Our research provides new insight into the IL-6/STAT3 signaling regulation in distinct macrophage populations and further proves the therapeutic potential of gp130 blockage for tumor treatment." (PMID 38274367, 2024). "We found that the activities of target genes regulated by NR3C1, STAT1, and STAT3 were higher in tumor tissues, implying that NR3C1, STAT1, and STAT3 played critical regulatory roles for the development of CTLA4+ T cell subsets." (PMID 38604154, 2024). "To explore the molecular underpinnings by which EHMF ameliorates skin photoaging, we analyzed the expression and phosphorylation profiles of critical proteins within the AKT and STAT3 signaling cascades in mice afflicted with skin photoaging." (PMID 39469625, 2024). "The demethylase FTO has been shown to be responsible for decreasing m6A methylation of Apolipoprotein E (APOE) mRNA and modulating the IL-6/JAK2/STAT3 signaling pathway, thereby inhibiting tumor glycolysis and abrogating tumor growth." (PMID 38902779, 2024). "One study in the mouse TNBC equivalent 4T1 cells showed that serine phosphorylated mitochondrial STAT3 can decrease apoptosis and promote tumor cell growth by decreasing the amount of reactive oxygen species (ROS) that is released from complex I." (PMID 38538285, 2024). "Although it has been reported that pharmacologically use of FGF15/19 leads to liver cell growth and neoplasia, NGM282, a full FGFR4 agonist, due to its inability to activate STAT3 pathway, it lacks tumor-promoting activity in mice." (PMID 38971765, 2024). "Subsequently, ccRCC tumor cells paracrinally activated STAT3 signaling in CAFs to transcriptionally regulate FGF7 expression." (PMID 39594574, 2024). "Key downstream factors of NF-κB such as IL-6 and cyclooxygenase-2 (COX2) not only play critical roles in tumor initiation and progression under the influence of NF-κB but are also involved in STAT3 activation." (PMID 39493763, 2024). "LRG1 induction in the tumor mass and systemically in cancer is most probably through IL-6 and STAT3, with contributions from other signaling pathways." (PMID 38745756, 2024).
tumor (continued). "The suppression of STAT3 leads to apoptosis, inhibition of growth, reduced tumor cell invasion, and increased sensitivity to treatment in BC cells." (PMID 39411137, 2024). "Pharmacological blockade of STAT3 or myMAF-specific genetic depletion of STAT3 restores an anti-tumour immune response and reduces metastases." (PMID 38678021, 2024). "It is recognized as an oncogene in tumor development, with abnormal STAT3 expression reported in nearly 70% of cancers." (PMID 39598398, 2024). "The results revealed the comparable binding affinity of [18F]FBNAF as the lead compound, high stability, and favorable pharmacokinetics, including tumor accumulation corresponding to STAT3 expression." (PMID 38834900, 2024). "Regarding tumor promotion, IL-17 secreted by Th17 cells can stimulate TCs through the IL-6/Stat3 signaling pathway, promoting their proliferation, migration, and invasion." (PMID 38755133, 2024). "Can the transcription factor STAT3 downregulate the expression of lncRNAs and thereby affect the biological phenotype of tumor cells?" (PMID 38172648, 2024). "The persistent activation of STAT3 maintains a pro-carcinogenic microenvironment and mediates tumour-promoting processes." (PMID 38347836, 2024). "IL-9-mediated STAT3 activation increases FAO in tumor Tc9 cells, increasing their longevity and antitumor ability." (PMID 39402302, 2024). "IL-6 can activate STAT3, and IL-6 is often elevated systemically and in the tumor microenvironment in patients with cancer." (PMID 38611065, 2024). "To determine the plausibility of these drugs in BCa cells, we examined the expression of STAT3 in BCa cells and found that all the cell line models expressed STAT3 and p-STAT3, thus allowing us to assess the anti-tumor effects of STAT3 inhibitors." (PMID 39273033, 2024). "Collectively, JAK2/STAT3/c‐Myc signaling axis activation by RNF122 was indicated to enhance tumor growth." (PMID 39218810, 2024). "A multitude of studies have demonstrated that CXCL12 fosters tumor growth and metastasis, and pharmacological interventions targeting the STAT3 pathway have proven efficacious for various cancers." (PMID 38920657, 2024). "Mechanistically, miR-101 suppresses T-ALL tumor development by targeting the CXCL12/ACKR3/STAT3 signaling pathway." (PMID 38920657, 2024). "Knockdown of IL20RA in CRC cell lines downregulates Janus kinase 1 (JAK1) and signal transducer and activator of transcription 3 (STAT3) and consistently suppress tumor growth." (PMID 39664380, 2024). "In retinoblastoma, high UBE2T expression enhances Th2 cell immune infiltration by activating the STAT3 pathway, promoting tumor formation and progression; however, further investigation into the specific UBE2T proteins involved in this activation is warranted." (PMID 39791716, 2024). "STAT3 is commonly found with stimulated activity in most human carcinoma cell lines and tumor tissues." (PMID 38397437, 2024). "In tumor initiation and progression, STAT3 acts as either tumor facilitator or tumor suppressor, playing a critical role in regulating cell proliferation, migration, apoptosis, and survival." (PMID 38849954, 2024). "The growth of lung cancer was significantly reduced by Resveratrol [Polygonaceae; Grape Skin], a metabolite rich in polyphenols, which achieved this by inhibiting M2-like polarization among TAM and decreasing p-STAT3 expression within tumor tissues." (PMID 38420194, 2024). "During the initial stages, IL-17 has a pronounced effect on transducing tumor cells to activate STAT3 signaling, along with its downstream effectors such as NF-κB and anti- apoptotic proteins." (PMID 38279220, 2024). "Further examination of gene expression profiles from 84 ESCC tumors identified that the chemokine CCL18 promotes tumor cell proliferation through the JAK2/STAT3 signaling pathway." (PMID 39415846, 2024).